IGHV3-73 (immunoglobulin heavy variable 3-73)
Description:
V region of the variable domain of immunoglobulin heavy chains that participates in the antigen recognition. Immunoglobulins, also known as antibodies, are membrane-bound or secreted glycoproteins produced by B lymphocytes. In the recognition phase of humoral immunity, the membrane-bound immunoglobulins serve as receptors which, upon binding of a specific antigen, trigger the clonal expansion and differentiation of B lymphocytes into immunoglobulins-secreting plasma cells. Secreted immunoglobulins mediate the effector phase of humoral immunity, which results in the elimination of bound antigens. The antigen binding site is formed by the variable domain of one heavy chain, together with that of its associated light chain. Thus, each immunoglobulin has two antigen binding sites with remarkable affinity for a particular antigen. The variable domains are assembled by a process called V-(D)-J rearrangement and can then be subjected to somatic hypermutations which, after exposure to antigen and selection, allow affinity maturation for a particular antigen.
Synonyms: IGHV373; VH
Gene: Immunoglobulin variable (V) gene on chromosome 14 (106,802,694 to 106,803,233, reverse strand). Ensembl gene ENSG00000211976.
Subcellular location: Secreted; Cell membrane
Gene Ontology:
Molecular function: antigen binding
Biological process: immunoglobulin mediated immune response
Cellular component: extracellular region; plasma membrane
Homologues: Orthologues: chimpanzee IGHV3-73 (88% identical), mouse Ighv7-3 (69% identical), mouse Ighv7-1 (66% identical), mouse Ighv7-4 (65% identical), mouse Ighv7-2 (62% identical). Paralogues in human: IGHV3-72 (87% identical), IGHV3-49 (87% identical), IGHV3OR15-7 (85% identical), IGHV3-15 (84% identical), IGHV3-23 (80% identical), IGHV3-74 (80% identical), IGHV3-64 (79% identical), IGHV3-35 (78% identical), IGHV3-64D (78% identical), IGHV3-66 (78% identical), IGHV3OR16-13 (78% identical), IGHV3-43 (77% identical), and 65 more.
Diseases named in the same sentence as IGHV3-73 in open-access papers:
IGHV3-73 is named in the same sentence as 3 diseases in open-access papers, as found by Europe PMC text mining. Sharing a sentence is not in itself a finding about the gene and the disease. The quoted sentences say what the papers report.
osteoporosis (1 paper, 2023). A condition of reduced bone mass, with decreased cortical thickness and a decrease in the number and size of the trabeculae of cancellous bone (but normal chemical composition), resulting in increased fracture incidence. "Then five key genes (CCR5, IAPP, IFNA4, IGHV3-73 and PTGER1) were identified and used as features to construct a predictive prognostic model for osteoporosis using the GSE7158 dataset." (PMID 37361541, 2023).
IGHV3-73 also shares sentences with these, for which no sentence is quoted: COVID-19 (1 paper); malaria (1).